PITPNM3 (PITPNM family member 3)
Description:
Catalyzes the transfer of phosphatidylinositol and phosphatidylcholine between membranes (in vitro) (By similarity). Binds calcium ions.
Synonyms: NIR1; RDGBA3; ACKR6; CORD5
Tractability: Antibody: UniProt places it where antibodies can reach, with high confidence; the Human Protein Atlas places it where antibodies can reach.
Gene: Protein-coding gene on chromosome 17 (6,451,263 to 6,556,555, reverse strand). Ensembl gene ENSG00000091622.
Subcellular location: Endomembrane system
Subcellular location (Human Protein Atlas): Plasma membrane
Pathways (Reactome):
Metabolism: Synthesis of PI
Gene Ontology:
Molecular function: calcium ion binding; protein binding; receptor tyrosine kinase binding; phosphatidylinositol transfer activity; phospholipase activity; metal ion binding
Biological process: phosphatidylinositol biosynthetic process; intermembrane lipid transfer; phospholipid transport
Cellular component: cytosol; cell body; endomembrane system
Genetic constraint (gnomAD): Loss-of-function variants: 26 observed, 101.85 expected, observed/expected ratio (o/e) 0.26, 90% interval 0.19 to 0.35. The upper end of that interval is the gene's LOEUF score, 0.35, which puts it in group 1 of 6, group 1 being the genes least tolerant of losing a copy. Missense variants: 1,083 observed, 1,366 expected, observed/expected ratio (o/e) 0.79, 90% interval 0.75 to 0.83. Synonymous variants: 578 observed, 566.52 expected, observed/expected ratio (o/e) 1.02, 90% interval 0.95 to 1.09.
Homologues: Orthologues: chimpanzee PITPNM3 (99% identical), macaque PITPNM3 (98% identical), pig PITPNM3 (95% identical), rat Pitpnm3 (95% identical), mouse Pitpnm3 (94% identical), guinea pig PITPNM3 (93% identical), dog PITPNM3 (88% identical), rabbit PITPNM3 (74% identical), tropical clawed frog pitpnm3 (73% identical), zebrafish pitpnm3 (63% identical). Paralogues in human: PITPNM2 (58% identical), PITPNM1 (49% identical), PITPNC1 (4% identical), PITPNB (2% identical), PITPNA (2% identical).
Diseases named in the same sentence as PITPNM3 in open-access papers:
PITPNM3 is named in the same sentence as 32 diseases in open-access papers, as found by Europe PMC text mining. Sharing a sentence is not in itself a finding about the gene and the disease. The quoted sentences say what the papers report.
breast carcinoma (26 papers, 2013 to 2024). "The interactions of CCL18 with the receptor phosphatidylinositol membrane-associated transfer protein 3 (PITPNM3) have been extensively studied in breast cancer." (PMID 39409924, 2024). "We have demonstrated that the presence of chemokine (C-C motif) ligand 18 (CCL18), a hallmark of M2 macrophages, promotes breast cancer metastasis through binding to its receptor PITPNM3 on breast cancer cells; this chemokine is also associated with a poor prognosis of patients with breast cancer." (PMID 26244871, 2015). "As a receptor of CCL18, PITPNM3 mainly expressed in human retina, brain, spleen, and breast cancer cells." (PMID 36850011, 2023). "Previously, we have revealed that PITPNM3 can promote breast cancer (BRCA) cell EMT transformation, migration, and invasion." (PMID 36285700, 2022). "High expression of PITPNM3 significantly predicts poor prognosis of breast cancer in TCGA BRCA, KM plotter BRCA, bc‐GenExMiner BRCA and marginally predicts poor overall survival of breast cancer in SYSU cohort." (PMID 36285700, 2022). "PITPNM3 has been demonstrated as a druggable target because it had been discovered to promote breast cancer, hepatocellular carcinoma[5a] and pancreatic ductal carcinoma[6a] metastasis and our systematic analysis revealed its oncogenic roles in pan‐cancer." (PMID 36285700, 2022). "We next evaluated PITPNM3 inhibitor C8018‐7840 for their metastasis inhibitory activities in human breast cancer cell lines." (PMID 36285700, 2022). "These compounds exhibit target‐specific inhibition of PITPNM3 signaling, thereby reducing metastasis of breast cancer cells." (PMID 36285700, 2022). "Small molecule inhibitors targeting PITPNM3 exhibit target‐specific inhibition of PITPNM3 signaling, thereby reducing metastasis of breast cancer." (PMID 36285700, 2022). "It is known that CCL18 initiates Pyk2 and Src phosphorylation leading to breast cancer metastasis via its functional GPCR PITPNM3." (PMID 29738483, 2018). "In breast cancer, CCL18 binds to phosphatidylinositol transfer protein membrane-associated 3 (PITPNM3) at the plasma membrane and induces phosphorylation of PLCγ1 and protein kinase C zeta (PKCζ)." (PMID 29636894, 2018). "Only PITPNM3 has been related to cancer and only breast cancer cells have been reported to express PITPNM3." (PMID 26919103, 2016). "Data from our previous studies showed that PITPNM3 is a putative receptor for CCL18 on the surface of breast cancer cells and that it mediates the effects of CCL18 by activating both the ERK and Akt/GSK-3β signaling pathways in cancer cells." (PMID 26416449, 2015). "Our previous data revealed that CCL18 promotes extracellular matrix adherence and breast cancer cell invasion by binding to its potential cognate surface receptor PITPNM3, whose expression is essential for CCL18-induced calcium influx and chemotaxis." (PMID 26416449, 2015). "Total RNA isolated from the PITPNM3/Nir1 expressing breast cancer cell line MDA-MB-231, served as a control for the detection of PITPNM3/Nir1 expression." (PMID 23874339, 2013). "PITPNM3/Nir1 was shown to be expressed in human retina, brain, spleen as well as ovary and recently it was also shown to be abundantly expressed in breast cancer cells." (PMID 23874339, 2013). "Besides, by using nanoparticle‐based delivery systems, these PITPNM3‐selective compounds loaded nanoparticles significantly repress metastasis of breast cancer in mouse xenograft models and organoid models." (PMID 36285700, 2022). "Besides, these PITPNM3 inhibitors exhibit PITPNM3‐specific inhibition and reduce metastasis of breast cancer cells." (PMID 36285700, 2022). "Therefore, PITPNM3 can be a target for therapy, for instance, pachymic acid, a lanostrane-type triterpenoid from P.cocos., suppressed breast cancer metastasis via inhibiting PITPNM3 expression." (PMID 35609322, 2022).
breast carcinoma (continued). "PITPNM3 is important in the migration and metastasis of cells of tumors such as hepatocellular carcinoma, breast cancer, non-small cell lung cancer, oral squamous cell carcinoma, ovarian cancer, pancreatic ductal adenocarcinoma, prostate cancer, and squamous cell carcinoma of the head and neck." (PMID 33114763, 2020). "Activated by PITPNM3, Pyk2 can activate Src in breast cancer cells." (PMID 33114763, 2020). "In addition, TAMs produce CCL18; binding of CCL18 to its specific receptor PITPNM family member 3 (PITPNM3) facilitates breast cancer metastasis through activation of intracellular calcium signal." (PMID 28356139, 2017). "The understanding of CCL18 function has been hampered until the recent identification of PITPNM3 (phosphatidylinositol transfer protein 3; also named PYK2 N-terminal domain interacting receptor 1, Nir1) in breast cancer, which has a high binding affinity for CCL18." (PMID 26919103, 2016). "PITPNM3/Nir1 was recently described to be a signaling receptor for CCL18 on breast cancer cells." (PMID 23874339, 2013). "Phosphatidylinositol Transfer Protein, Membrane-Associated 3 (PITPNM3), also named PYK2 N-terminal domain interacting receptor 1, has been reported to have high expression in different cancers, such as oral squamous cell carcinoma, non-small cell lung cancer, and breast cancer." (PMID 35609322, 2022). "Thus, CCL18 and/or its potential receptor PITPNM3 may serve as therapeutic targets for inhibiting angiogenesis in breast cancer, particularly for patients with resistance to anti-VEGF monotherapy." (PMID 26416449, 2015). "The identification of PITPNM3/Nir1 as a PTX-sensitive cell surface receptor responsible for the CCL18 induced migration of human breast cancer cells indicated that this could be the receptor for this chemokine on leukocytes, but unfortunately we have shown that this seems not to be the case." (PMID 23874339, 2013). "Since PITPNM3 can be activated by binding with C‐C Motif Chemokine Ligand 18 (CCL18), the relationship between CCL18, PITPNM3 and breast cancer prognosis was determined." (PMID 36285700, 2022). "In breast cancer, CCL18 produced by TAMs has been reported to promote cancer metastasis via PITPNM3-dependent calcium signaling activation." (PMID 33052231, 2020). "In addition, while CCL18 promoted the invasion and metastasis of breast cancer, the suppression of PITPNM3 abolished these effects, what may confirm the critical role of TAM-derived CCL18 in promoting breast cancer metastasis via its atypical chemokine receptor, PITPNM3." (PMID 32456359, 2020). "In human breast cancer xenografts in humanized mice, blocking the recruitment of naive CD4+ T cells into tumor by knocking down the expression of PITPNM3, a CCL18 receptor, significantly reduces intratumoral Tregs and inhibits tumor progression." (PMID 28290464, 2017). "As the key functional receptor for CCL18, PITPNM3 is expressed primarily on the cell surface of tumor cells and it has been reported that TAM secreted CCL18 interacted with its receptor PITPNM3 to promote breast cancer metastasis and angiogenesis." (PMID 36850011, 2023). "PITPNM3 and CCR8 are reported CCL18 receptors on breast cancer cells and Th2 cells, respectively." (PMID 28290464, 2017). "Therefore, we examined the expression of PITPNM3 and CCR8 in T cell subsets from PB of breast cancer patients." (PMID 28290464, 2017). "PITPNM3 overexpression was reported in breast cancer tissue and cancer cell lines, independent of the CCL18+ TAM counts." (PMID 26919103, 2016). "Its receptor has remained elusive since its cloning in 1997, although it has been reported to induce migration of breast cancer cells by signaling through PITPNM3, but we show that this receptor is not expressed on lymphocytes." (PMID 23874339, 2013).
breast carcinoma (continued). "In addition, CCL18 can bind with PITPNM3, inducing EMT, migration, and invasion of non-small cell lung cancer and breast cancer via PI3K/Akt/GSK3β/Snail signaling pathway and engulfment and cell motility 1/dedicator of cytokinesis protein 4 CRK binding protein signaling pathway, respectively." (PMID 35609322, 2022).
hepatocellular carcinoma (6 papers, 2018 to 2022). A malignant tumor that arises from hepatocytes. "PITPNM3, one of member of a large family of G protein-coupled receptors, promotes the development of different cancer, such as in hepatic carcinoma, mitofusin-2 could interact with transcription factor SP1 to suppress PITPNM3 expression, which contributed to the inhibition of tumor." (PMID 35609322, 2022).
breast tumor (3 papers, 2013 to 2023). "It has been well established that PITPNM3 is a functional receptor of CCL18 in breast tumor cells and T lymphocytes." (PMID 36418470, 2023). "PITPNM3 has been proven to be a functional CCL18 receptor in breast tumor cells and T lymphocytes, while CCR6 and CCR8 have been proven to be expressed in T lymphocytes." (PMID 36418470, 2023). "To confirm the role of PITPNM3 in naive CD4+ T cell recruitment to breast tumors and elucidate the role of naive CD4+ T cell infiltration in Treg generation and cancer progression in vivo, we employed a humanized mouse tumor model." (PMID 28290464, 2017).
liver cancer (3 papers, 2022 to 2023). An epithelial or non-epithelial malignant neoplasm that arises from the liver. "It was reported that CCL18/PITPNM3 interaction could also promote liver cancer migration, invasion, EMT, and the progression of pancreatic ductal carcinoma." (PMID 36850011, 2023). "Additionally, previous study showed that CCL18/PITPNM3 activated NF-kB signaling to enhance migration, invasion, and EMT of liver cancer cells." (PMID 35609322, 2022).
pancreatic cancer (3 papers, 2018 to 2024). "PITPNM3 has also been found to promote the progression of various tumours, such as breast and pancreatic cancer, which is an emerging therapeutic target in cancer." (PMID 39355773, 2024). "In this study, our work provides the valid evidence for reciprocal signaling interactions between TAMs and pancreatic cancer cells, shedding new light on the utilization of CCL18/PITPNM3/NF-kB/VCAM-1 axis as a potential novel therapeutic target for the treatment of pancreatic cancer." (PMID 29670110, 2018). "Our study provides the first connection between CCL18/PITPNM3/NF-kB/VCAM-1 axis and PDAC progression and the Warburg effect, raising the possibility of new options for clinical interventions for pancreatic cancer patients." (PMID 29670110, 2018). "In pancreatic cancer, TAM-M2 cells have been found to enhance aerobic glycolysis in pancreatic cancer cells, thereby promoting tumor invasion and metastasis via the secretion of the chemokine CCL18, which interacts with its receptor, PITPNM3." (PMID 39227970, 2024).
oral squamous cell carcinoma (2 papers, 2020 to 2022). "PITPNM3 causes signal transduction through the JAK2→STAT3 pathway, leading to the proliferation, migration, and EMT of oral squamous cell carcinoma cells." (PMID 33114763, 2020). "CCL18/PITPNM3 axis also activates JAK2/STAT3 signaling pathway to promote the growth and metastasis of oral squamous cell carcinoma cells." (PMID 35609322, 2022).
esophageal cancer (1 paper, 2023). A primary or metastatic malignant neoplasm involving the esophagus. "Similarly, we discovered that CCL18 could promote proliferation of esophageal cancer cells via its interaction with PITPNM3." (PMID 36850011, 2023). "The esophageal cancer cell line EC-109, which expressed PITPNM3 but not CCL18, was selected in the subsequent in vitro experiment." (PMID 36850011, 2023).
gastric cancer (1 paper, 2016). A primary or metastatic malignant neoplasm involving the stomach. "This disparity in PITPNM3 expression between breast and gastric cancers indicates that the two malignancies may respond differently to CCL18 and explains their distinct clinical outcomes." (PMID 26919103, 2016). "Interestingly, almost no PITPNM3 expression was detected in gastric cancer tissue samples by IHC." (PMID 26919103, 2016).
intrahepatic cholangiocarcinoma (1 paper, 2022). A carcinoma that arises from the intrahepatic bile duct epithelium in any site of the intrahepatic biliary tree. "However, the role of PITPNM3 in intrahepatic cholangiocarcinoma (ICC) is unclear." (PMID 35609322, 2022).
lymph node metastasis (1 paper, 2022). "In detail, the clinicopathologic characteristics of tumor size and lymph node metastasis had significant difference between the high expression of PITPNM3 (N = 22) and low expression of PITPNM3 (N = 18) in ICC tissues." (PMID 35609322, 2022).
lymphoma (1 paper, 2025). A malignant (clonal) proliferation of B- lymphocytes or T- lymphocytes which involves the lymph nodes, bone marrow and/or extranodal sites. "Although CCR3, CCR6, CCR8, PITPNM3, and GPER1 encode receptors of CCL18, only CCR6 was expressed in the lymphoma cells." (PMID 39894788, 2025).
retinal degeneration (1 paper, 2025). Degeneration of the retina. "First, we have limited understanding of the exact molecular mechanisms by which PITPNM3 mutations lead to retinal degeneration." (PMID 41148841, 2025). "Additionally, RD1 retinal degeneration mutations in the mouse line are a confounding factor as contamination renders it difficult to isolate the study results to the effects of PITPNM3 mutation." (PMID 41148841, 2025). "Previous preclinical models have shown that the drosophila homologue of PITPNM3, rdgB, is involved in photoreceptor response and prevention of retinal degeneration." (PMID 41148841, 2025). "PITPNM3-related retinal degeneration is a progressive condition that develops over time; thus, a relatively short follow-up limits the ability to observe more pronounced phenotypic changes." (PMID 41148841, 2025). "Furthermore, investigating the impact of oxidative stress and employing alternative models like zebrafish or fruit flies could offer additional insights, contributing to a more holistic understanding of PITPNM3′s involvement in retinal degeneration." (PMID 41148841, 2025). "The incorporation of additional genetic variants, such as PDE6, which exhibits phenotypic similarities to PITPNM3, and the consideration of various disease stages, could provide complementary insights, leading to a more thorough comprehension of PITPNM3′s role in retinal degeneration." (PMID 41148841, 2025).
retinal disease (1 paper, 2025). "PITPNM3 has been identified as a crucial gene associated with various phenotypes of retinal disease in humans; however, detailed mechanisms through which PITPNM3 mutations result in these conditions are not fully understood." (PMID 41148841, 2025).
cancer (26 papers, 2012 to 2024). A tumor composed of atypical neoplastic, often pleomorphic cells that invade other tissues. "The same group identified a membrane-associated phosphatidylinositol transfer protein 3, PITPNM3 (or Nir1) as CCL18 receptor on cancer cells." (PMID 39044824, 2024). "This pan‐cancer analysis identifies oncogenic roles of membrane‐associated phosphatidylinositol transfer protein 3 (PITPNM3), which is crucial for cancer metastasis." (PMID 36285700, 2022). "Pan‐cancer analysis identifies oncogenic roles of membrane‐associated phosphatidylinositol transfer protein 3 (PITPNM3)." (PMID 36285700, 2022). "In this study we performed systematic analysis of PITPNM3 in pan‐cancer and revealed oncogenic role of PITPNM3." (PMID 36285700, 2022). "It promotes cancer cell invasion by stimulating clustering of integrins and enhances adhesion of cancer cells on lung tissue through its receptor PITPNM3." (PMID 36430404, 2022). "Knockdown of PITPNM3 by siRNAs will significantly abrogate CCL18 conducted cell metastasis in these 13 cancer cell lines." (PMID 36285700, 2022). "Since PITPNM3 inhibition had little impact on cancer cell proliferation or apoptosis, 54 compounds with less toxicity were selected for the next screening round." (PMID 36285700, 2022). "This provided new small molecular inhibitors to reverse PITPNM3‐related metastasis of different cancers and potentially break the bad feedback loop between tumor microenvironment and tumor." (PMID 36285700, 2022). "CCL18 is thought to promote the invasiveness of cancer cells by triggering integrin clustering and enhancing their adherence to the extracellular matrix, and a receptor (PITPNM3) for this cytokine has been recently identified." (PMID 22629457, 2012). "Additionally, through producing CCL18, which binds to PITPNM3 on the cancer cell membrane, TAMs in breast cancer increase the invasiveness of cancer cells." (PMID 36825088, 2023). "Previous studies reported that PITPNM3 shows high expression in different cancers." (PMID 35609322, 2022). "To determine whether patients carrying other types of malignancy could benefit from targeting PITPNM3 therapy, we performed a systematic analysis of PITPNM3 in pan‐cancer." (PMID 36285700, 2022). "Above all, CCL18/CCL3 blockade could elicit significant antitumor effects in ESCC through preventing the infiltration of tumor-associated macrophages and proliferation of ESCC cancer cells, which might be mediated by CCL3/CCR1, CCL3/CCR5 and CCL18/PITPNM3 pathways." (PMID 36850011, 2023). "Therefore, oncogenic PITPNM3 is considered a potential target for reversing cancer metastasis." (PMID 36285700, 2022). "In The Cancer Genome Atlas (TCGA) and Sun Yat‐Sen University (SYSU) cohort, the expression of PITPNM3 is much high in triple negative cancer than solid normal." (PMID 36285700, 2022). "PITPNM3 and CCL18 are reported to participate in cancer cell activation, migration, and the progress of immune tolerance." (PMID 35609322, 2022). "It includes a description of the signal transduction from PITPNM3 in CCL18-dependent migration, invasion, and epithelial-to-mesenchymal transition (EMT) cancer cells." (PMID 33114763, 2020).